RNU6-382P (RNA, U6 small nuclear 382, pseudogene)
Gene: Small nuclear RNA gene on chromosome X (147,827,279 to 147,827,384, forward strand). Ensembl gene ENSG00000202051.
Homologues: Orthologues: chimpanzee U6 (100% identical), macaque U6 (89% identical), pig U6 (74% identical), guinea pig U6 (71% identical), mouse Gm55757 (61% identical). Paralogues in human: RNU6-1042P (89% identical), RNU6-116P (87% identical), RNU6-211P (87% identical), RNU6-698P (87% identical), RNU6-1060P (85% identical), RNU6-1152P (85% identical), RNU6-1316P (85% identical), RNU6-15P (85% identical), RNU6-589P (85% identical), RNU6-1145P (84% identical), RNU6-1303P (84% identical), RNU6-142P (84% identical), and 1284 more.